AR (androgen receptor)
Diseases named in the same sentence as AR in open-access papers (continued):
Sharing a sentence is not in itself a finding about the gene and the disease.
prostate carcinoma (continued). "We recently hypothesised that the inverse relationship between stromal AR level and prostate cancer outcome is the result, in part, of changes in the production and regulation of fibroblast ECM." (PMID 28117763, 2017). "Targeting the PI3K and androgen receptor pathways may be an approach to treat therapy-resistant prostate cancer." (PMID 29100331, 2017). "However, BRACHYURY/T was shown to bind to the promotor of the androgen receptor (AR) and regulate AR expression in prostate cancer cells." (PMID 29019938, 2017). "Androgen synthesis inhibitors (GnRH agonists/antagonists, abiraterone acetate) and AR inhibitors (enzalutamide, bicalutamide) play a major role in treating prostate cancer, another androgen driven disease, and possibly may benefit patients with PSCC." (PMID 28423512, 2017). "Since it was discovered that prostate cancer cell growth is dependent on the promoting effect of male hormone supplied through peripheral blood circulation, ADT targeting AR and circulating androgen has been the main therapeutic method to treat prostate cancer patients during the past 4 decades." (PMID 28415688, 2017). "However, this study is the first to suggest simultaneous inhibition of AhR and Src to inhibit AR signaling and prostate cancer cell growth." (PMID 28671964, 2017). "It is inversely associated with advanced disease and poor outcome of prostate cancer patients, and miR-205 levels in cancer tissues exhibit a negative correlation with AR immunoreactivity." (PMID 28783103, 2017). "A microarray analysis on AR-positive prostate cancer cell lines identified 16 AR-responsive miRNAs." (PMID 28783103, 2017). "First, AR can increase spatial association of the transmembrane protease, serine 2 (TMPRSS2) gene and ETS-related gene (ERG) and mediate TMPRSS2-ERG gene fusion, which is a clinical marker of prostate cancer." (PMID 29149895, 2017). "Comparably, CTCs in prostate cancer can display androgen receptor (AR) expression and signaling transitions that could provide valuable information for second-line therapy with adequate inhibitors." (PMID 27683128, 2017). "Notably, another study also observed the importance of TET2 in prostate cancer by regulating AR activity." (PMID 28783103, 2017). "Whilst androgen action through the androgen receptor (AR) is a well-established component of prostate cancer biology, it has been becoming increasingly apparent that changes in AR signalling in the surrounding stroma can dramatically influence tumour cell behavior." (PMID 28117763, 2017). "CAG repeat deletion in the androgen receptor (AR) gene can result in a high transcriptional activity of the AR protein, which may potentially lead to progression of prostate cancer." (PMID 28475635, 2017). "Next, We examined whether the observed mutual exclusivity between AR, HOXC6 and NKX2-2 overexpression is specifically associated with prostate cancer, or represents an intrinsic property of tumorigenesis." (PMID 28397780, 2017). "Stopping such a protein from binding with the androgen receptor might represent a new way to treat prostate cancer; but first it will be important to understand how this interaction actually regulates the activity of the receptor." (PMID 28826504, 2017). "However, additional studies must be performed to clarify the extent to which reductions in PPARγ function contribute to AR's ability to regulate prostate cancer proliferation and metabolism." (PMID 29181019, 2017). "However, the effect of PPARγ ligands on AR activity appears to vary between AR-positive, castration-sensitive and AR-positive, castration-resistant human prostate cancer cells." (PMID 29181019, 2017). "Later, PCA patient derived blood specimens were tested for CTC detection using CSV positive cell capture method and the results indicated that the cells detected were positive for androgen receptor staining thus validating the prostate cancer identity of the CTC." (PMID 28521303, 2017).
prostate carcinoma (continued). "The current study adds to this by suggesting that the link between PKC and AR phosphorylation is also present in hormone naïve prostate cancer tissue and therefore may have important implications in both early and late stages of the disease." (PMID 27902483, 2017). "MDV3100 and ARN509 are two AR antagonists for the treatment of prostate cancer patients." (PMID 28326012, 2017). "The androgen receptor (AR) plays a central role in the development of prostate cancer (PCa)." (PMID 28826504, 2017). "This review will discuss our current understanding of the role of AR and PPARγ within the prostate and how interactions between these two signaling pathways can influence the growth and development of normal prostate as well as prostate cancer." (PMID 29181019, 2017). "In addition, there is increased transcriptional activity of AR within castration-resistant prostate cancer by hypoxia." (PMID 28416760, 2017). "In this study we have investigated whether the pharmacological inhibition of USP7, by impairing the stability of AR, is able to weaken the AR-dependent proliferation of prostate cancer cells." (PMID 28415632, 2017). "Thus, we posit that CREB3L4 is an essential mediator of AR-IRE1α-induced prostate cancer progression." (PMID 28338058, 2017). "While PPARγ ligands suppress AR activation in AR-positive, castration-sensitive prostate cancers via mechanisms that are independent of PPARγ, ligand-induced activation of PPARγ increases AR signaling in AR-positive, castration-resistant prostate cancer cells." (PMID 29181019, 2017). "In agreement with our results, two published reports have shown that in advanced, refractory prostate cancer, both docetaxel and paclitaxel improve survival, reduce pain, and decrease expression of AR levels and PSA expression, although with significant side effect." (PMID 29552052, 2017). "Current strategies to target prostate cancer are based on differential expression of prostate-associated genes (e.g. PSA; prostatic acid phospahatase (PAcP); prostate specific stem cell antigen (PSCA); androgen receptor (AR), etc.)." (PMID 28663562, 2017). "Further, these factors may cooperate; AR/RUNX2 complexes are important drivers of prostate cancer stem cell expansion." (PMID 28412963, 2017). "Given that ERG is able to antagonize AR function in prostate cancer cells, it will be interesting to explore whether ERG regulation of YAP1 also relies on antagonizing the repressing actions of the AR/DNMT3a complex." (PMID 29383141, 2017). "Given that HOXB13 is known to interact with AR signaling and plays an important role in prostate development, the HOXB13 variation may also disrupt the AR pathway and promote prostate cancer initiation and progression." (PMID 28598379, 2017). "Therefore, the effects of NBBS on AR and subsequent decrease in PC-3 proliferation can be explored to maximize its potential for the chemoprevention of prostate cancer." (PMID 28286531, 2017). "The prognostic impact of the loss of RBM3 expression is markedly pronounced in estrogen receptor (ER)-positive breast cancer compared with ER-negative tumors, whereas RBM3 overexpression is a good prognostic marker in prostate cancer, which is governed by androgen receptor (AR) signaling." (PMID 28118608, 2017). "Since activation of NF-κB and reactivation of AR signaling are involved in prostate cancer progression and CRPC development, we reason that androgen depletion and melatonin repletion will help to prolong the progression-free survival of these patients by delaying CRPC development." (PMID 28561752, 2017). "However, androgen-deprivation therapies cannot completely abolish AR signaling and most prostate cancers become eventually castration-resistant prostate cancer (CRPC), because of the occurence of AR gene point mutations or truncation." (PMID 28415632, 2017).
prostate carcinoma (continued). "Given our data that surface Hsp90 may ‘mark’ a population of stem-like prostate cancer cells, we next evaluated whether surface Hsp90 correlated with AR expression." (PMID 28038472, 2017). "AR plays an important role in the process of prostate cancer growth." (PMID 29029409, 2017). "The function of androgen receptor (AR) is essential for the progression of prostate cancer." (PMID 28397780, 2017). "Interestingly, PPAR-γ agonists are currently in phase 2 clinical trials for AR-independent prostate cancer." (PMID 29023443, 2017). "Therefore it is possible that RNF6 and USP22 contribute to prostate cancer progression by changing AR activity and stability." (PMID 27057639, 2016). "Prostate cancer growth relies on androgens and the androgen receptor (AR) pathway." (PMID 27363033, 2016). "Besides being a transcription factor, AR has a potential role in DNA licensing for AR-expressing prostate cancer cells." (PMID 27835608, 2016). "Taken together, miR-135a was directly upregulated by AR in prostate cancer cells." (PMID 27323416, 2016). "Further investigations on the pathophysiologic effects of PC-1 on AR function may reveal that PC-1 can serve as a valuable target in controlling prostate cancer progression." (PMID 27835608, 2016). "AR is one of most critical effectors in prostate cancer development and progression." (PMID 27626693, 2016). "We propose that a novel regulatory axis, HIFs/PHF8/AR, exists in prostate cancer and targeting this axis could be a potential therapeutic strategy in combating castration-induced CRPC." (PMID 27991916, 2016). "The design of ligands able to specifically target the NTD of AR is a subject of intensive research, as this domain is involved in the constitutive and unfaithful induction of the gene expression in the case of castration-resistant prostate cancer." (PMID 27583469, 2016). "In addition to aberrant AR signaling, prostate cancer cells exhibit metabolic rewiring, including upregulation of fatty acid synthesis." (PMID 27248322, 2016). "Although KLF4 activity is repressed in several cancers and can have a tumor-suppressive effect, the specific role of KLF4 in AR pathway-activated prostate cancer remains unclear." (PMID 27991915, 2016). "Furthermore, the functional relationship between PHF8 and the AR signaling pathway and prostate cancer progression following castration treatment remain poorly understood." (PMID 27991916, 2016). "In another study, it identified that downregulation of miR-31 may disrupt normal cell homeostasis and contribute to evolution and progression of prostate cancer through promotion of androgen receptor signaling." (PMID 27174918, 2016). "Besides AR signaling, recent evidences suggest other signaling pathways involved in prostate cancer development and progression." (PMID 27323416, 2016). "The vast majority of prostate cancer deaths are due to castration-resistant prostate cancer (CRPC) – the lethal form of the disease that has progressed despite therapies that interfere with activation of androgen receptor (AR) signaling." (PMID 27276681, 2016). "Novel approaches to targeting AR are worthy of investigation and might be of clinical use in the treatment of prostate cancers that will otherwise overcome current anti-androgen treatments, leading to clinical relapse and the emergence of CRPC." (PMID 27729622, 2016). "Recent studies have shown that AMPK activation suppresses AR levels and inhibits prostate cancer cell proliferation and tumor growth, and that this response is magnified in the presence of an AR antagonist, similar to our observations with ACLY inhibition in this study." (PMID 27248322, 2016). "The expression of RUNX2 and androgen receptor (AR) predicts prostate cancer recurrence." (PMID 27007162, 2016).
prostate carcinoma (continued). "However, it has been reported that enzalutamide promotes prostate cancer metastasis in different models, moreover, in our study we found that AR knockdown promotes invasion and migration of prostate cancer cells while DANCR knockdown reduces the promotion." (PMID 27191265, 2016). "The AR-inhibitory function of PRMT5 is restricted to TMPRSS2:ERG-positive prostate cancer cells." (PMID 27183006, 2016). "Resveratrol can also regulate androgen receptor (AR)-mediated actions as a chemopreventive agent against prostate cancer: it inhibited androgen-stimulated cell growth and gene expression by repressing the expression and function of the AR in LNCaP prostate cancer cells." (PMID 27231938, 2016). "Utilizing a previously published model of stepwise prostate carcinogenesis and prostate cancer cell lines we therefore undertook a further examination of conditions for the restriction of AR and classical AR target gene expression in different cellular contexts." (PMID 27378372, 2016). "Moreover, rosemary extract decreased androgen receptor expression and suppressed tumor growth in human prostate cancer cell lines, such as 22Rv1 and LNCaP." (PMID 27529277, 2016). "DATS is also shown to suppress AR function in prostate cancer cells." (PMID 27019751, 2016). "In order to determine whether PC-1 suppressing AR protein stability and transcriptional activity can attenuate AR inhibition on prostate cancer cell growth stimulated with R1881, MTT assay was performed." (PMID 27835608, 2016). "Since previous studies have shown that miR-21 is an AR-regulated miRNA in prostate cancer where it promotes cell growth, we questioned if the inhibitory effect observed in MCF-7 is exclusively related to the cell system used or it is a normal response of the mammary epithelium." (PMID 26862856, 2016). "It has been reported that mtDNA depletion may result in androgen-independent growth and a CRPC phenotype when mtDNA replication is inhibited in the AR+ prostate cancer cells." (PMID 27248169, 2016). "PI3K/AKT signalling and AR signalling increase SKP2 abundance in prostate cancer cells." (PMID 26682011, 2016). "Moreover, AR itself is a target of miR-34a AR signaling is therefore much enhanced in prostate cancer cells through this loop." (PMID 27438705, 2016). "Intriguingly, a novel dual function ACLY inhibitor/AMPK activator has entered clinical trials for metabolic diseases; such a compound could be attractive to test for efficacy in prostate cancer along with an AR antagonist." (PMID 27248322, 2016). "This study begins to elucidate the mechanism of TQ on inhibiting AR protein expression that may be through its activity to alter the redox state in prostate cancer cells." (PMID 26986969, 2016). "The molecular mechanisms that underlie AR transcriptional induction in normal prostate epithelial homeostasis and to which extent these mechanisms are retained in putative prostate cancer stem cells (CSCs) are not understood." (PMID 27378372, 2016). "Through expression profiling and functional studies, we identified NFKBIA (IκBα) as a critical mediator of this therapy, and in doing so provided novel insight into AR signaling and how this might be effectively targeted in prostate cancer." (PMID 26907477, 2016). "Some AR cofactors are known to be upregulated or downregulated in patients with prostate cancer." (PMID 27493956, 2016). "Androgen receptor (AR) plays a critical role in the development and treatment of prostate cancer." (PMID 27191265, 2016). "Notably, one group of genes with very strong negative correlations (≤-0.9) to radiomic features were found to be associated with the AR signaling genes: KLK2, KLK3, HOMER2, BMPR1B, or belong to validated prostate cancer classifiers: CHRNA2, MT1H, DPP4, MYBPC1." (PMID 27438142, 2016).
prostate carcinoma (continued). "One study reported that enzalutamide (an AR receptor antagonist)-induced FDHT uptake changes in metastatic lesions could be considered a surrogate marker for response of prostate cancer metastases with AR overexpression to ADT." (PMID 26894753, 2016). "Additionally, initiation and progression of prostate cancers appear to be coupled with aberrant activation of AR signaling." (PMID 27144435, 2016). "This study showed that AR is a pivotal factor in prostate cancer development." (PMID 27399684, 2016). "One mechanism of resistance of prostate cancer (PCa) to enzalutamide (MDV3100) treatment is the increased expression of AR variants lacking the ligand binding-domain, the best characterized of which is AR-V7." (PMID 27588408, 2016). "Recently, we identified an AR-miR-204-XRN1-miR-34a regulatory circuitry in prostate cancer cells." (PMID 27438705, 2016). "It has been noticed for years that in the AR- prostate cancers, the mtDNA depletion protects cells from anoikis and gives a cell metastasis potential, which might be powered by metabolic reprogramming towards Warburg effect." (PMID 27248169, 2016). "Taken together, these data suggest that KLF4 expression is upregulated by AR in prostate cancer." (PMID 27991915, 2016). "Taking this into consideration, ZFP91 may potentially influence androgen receptor signaling in prostate cancer cells and therefore affect the biology of prostate cancer." (PMID 27975057, 2016). "Here we report that DNAH8 functions in prostate cancer and affects AR signaling." (PMID 27363033, 2016). "For example, tissue-specific markers such as NKX3.1, prostate-specific acid phosphatase (PSAP), and androgen receptor (AR) (prostate cancer markers) or PAX8 (kidney cancer marker) could be used to confirm the origin of the detected tumor cells." (PMID 27634877, 2016). "Interestingly, a second regulator of EMT, Twist, was unable to induce EMT or AR expression in prostate cancer cells using similar methodology." (PMID 27409172, 2016). "This property may be exploited to design future therapeutic strategies targeting AR related diseases such as the spinal bulbar muscular atrophy or prostate cancer." (PMID 27583469, 2016). "Overexpression and enhanced activity of calpain-2 also induces an increase in the fragmental cleavage of AR and FlnA, which may contribute to the development of an aggressive phenotype of prostate cancer." (PMID 27689993, 2016). "Therefore, blocking this pathway through androgen deprivation and AR antagonists is the mainstay of prostate cancer treatment." (PMID 27363033, 2016). "Interestingly, the LNCaP prostate cancer cell line, which expresses functional AR exhibited distinct apoptotic sensitivity to Nutlin-3, an observation that is thus far unexplained." (PMID 27729622, 2016). "It is intriguing to investigate whether there is any link between IL-17RA and AR in the context of GSK3's regulatory functions in prostate cancer." (PMID 26871944, 2016). "In the presence of USP22, AR protein levels are increased in prostate cancer cell lines." (PMID 27057639, 2016). "Knowing that the steady state concentration of bicalutamide in the serum of prostate cancer patients is 8.9 μg/mL or approximately 20 μM, we were surprised to find that in our assay this drug activated the wild-type AR in the same concentrations range (approximately 16 μM)." (PMID 26813233, 2016). "FOXA1 is also a pioneer factor for AR DNA binding in prostate cancer cells and this function may be preserved in breast cancer expressing AR." (PMID 26797644, 2016). "Abnormal AR functions, such as functional activation, are increasingly recognized in prostate cancer development and progression, with large bodies of evidence indicating that AR activities and levels are precisely modulated by many cofactors at both transcriptional and post-translational levels." (PMID 27835608, 2016). "Androgen receptor (AR) plays a crucial role in prostate cancer (PCa)." (PMID 27659526, 2016).